KRT40 (keratin 40)
Description:
May play a role in late hair differentiation.
Synonyms: CK-40; K40; KA36; FLJ36600
Tractability: No criterion of Open Targets' tractability assessment is met for any kind of drug.
Gene: Protein-coding gene on chromosome 17 (40,977,715 to 40,987,135, reverse strand). Ensembl gene ENSG00000204889.
Pathways (Reactome):
Developmental Biology: Formation of the cornified envelope; Keratinization
Gene Ontology:
Molecular function: protein binding; structural constituent of skin epidermis; structural molecule activity
Biological process: epithelial cell differentiation; intermediate filament organization; morphogenesis of an epithelium
Cellular component: cytoskeleton; cytosol; keratin filament
Genetic constraint (gnomAD): Loss-of-function variants: 42 observed, 41.61 expected, observed/expected ratio (o/e) 1.01, 90% interval 0.79 to 1.31. The upper end of that interval is the gene's LOEUF score, 1.31, which puts it in group 5 of 6, group 1 being the genes least tolerant of losing a copy. Missense variants: 526 observed, 513.02 expected, observed/expected ratio (o/e) 1.03, 90% interval 0.95 to 1.1. Synonymous variants: 198 observed, 208.48 expected, observed/expected ratio (o/e) 0.95, 90% interval 0.85 to 1.07.
Homologues: Orthologues: chimpanzee KRT40 (97% identical), macaque KRT40 (96% identical), dog KRT40 (83% identical), rat Krt40 (80% identical), rabbit KRT40 (79% identical), mouse Krt40 (79% identical), pig KRT40 (77% identical), guinea pig KRT40 (72% identical). Paralogues in human: KRT35 (60% identical), KRT36 (59% identical), KRT32 (58% identical), KRT31 (57% identical), KRT34 (57% identical), KRT33A (56% identical), KRT33B (55% identical), KRT38 (50% identical), KRT39 (50% identical), KRT37 (49% identical), KRT14 (42% identical), KRT15 (42% identical), and 56 more.
Diseases named in the same sentence as KRT40 in open-access papers:
KRT40 is named in the same sentence as 10 diseases in open-access papers, as found by Europe PMC text mining. Sharing a sentence is not in itself a finding about the gene and the disease.
KRT40 shares sentences with these, for which no sentence is quoted: adenocarcinoma (1 paper); breast tumors (1); cardiac disease (1); Epstein-Barr virus infection (1); Huntington disease (1); infection (1); large cell neuroendocrine carcinoma (1); ovarian carcinoma (1); progeria (1); squamous cell carcinoma (1).